ITGB2 (integrin subunit beta 2)
Diseases named in the same sentence as ITGB2 in open-access papers (continued):
Sharing a sentence is not in itself a finding about the gene and the disease.
carotid atherosclerosis (2 papers, 2022 to 2024). A thickening and loss of elasticity of the walls of carotid arteries that occur with formation of atherosclerotic plaques. "According to previous studies, ITGB2 is related to the occurrence of many diseases, including carotid atherosclerosis, necrotizing enterocolitis, and cancer." (PMID 36362654, 2022). "The expression of ITGB2 was upregulated in atheroma plaque compared with intact tissue and involved in the development of carotid atherosclerosis." (PMID 36362654, 2022).
coronary heart disease (2 papers, 2022 to 2023). "On the other hand, the ITGB2 SNP rs2070947 has been reported to show a significant difference in the recessive model among coronary heart disease patients in Chinese Han population." (PMID 37644537, 2023).
cutaneous melanoma (2 papers, 2019 to 2021). A primary melanoma arising from atypical melanocytes in the skin. "However, the prognostic value of ITGB2 in cutaneous melanoma has not yet been reported." (PMID 31212865, 2019).
epilepsy (2 papers, 2013 to 2017). A brain disorder characterized by episodes of abnormally increased neuronal discharge resulting in transient episodes of sensory or motor neurological dysfunction, or psychic dysfunction. "Down-regulation of adhesion molecules, including integrin (ITGB1, ITGB2) and cadherin family members (CDH11) in the peritumoral tissue of the subjects with epilepsy also serve to validate our study, as they have also been found to contribute to the cell biology underlying epileptogeneis." (PMID 23418513, 2013).
Fanconi anemia (2 papers, 2011 to 2025). Fanconi anemia (FA) is a hereditary DNA repair disorder characterized by progressive pancytopenia with bone marrow failure, variable congenital malformations and predisposition to develop hematological or solid tumors. "For instance, it has a positive clinical impact on ADA deficiency, Wiskott-Aldrich syndrome (WAS), Fanconi anemia, and in variants affecting DOCK8, ITGB2, or CXCR4." (PMID 40711587, 2025).
glaucoma (2 papers, 2019 to 2024). Increased pressure in the eyeball due to obstruction of the outflow of aqueous humor. "In the DBA/2J mouse model of glaucoma, the genetic subunits of CR3, encoded by Itgam and Itgb2, are both highly expressed in the monocytes that infiltrate the ONH early in the development of glaucoma." (PMID 38396986, 2024). "We have previously reported important roles for the complement pathways in glaucoma and the genetic subunits of CR3 (Itgam and Itgb2) are both highly expressed in our infiltrating monocytes, represented in the top 1.5% of expressed genes." (PMID 30670050, 2019).
gout (2 papers, 2023 to 2024). A condition characterized by painful swelling of the joints, which is caused by deposition of urate crystals. "Compared with remission, we observed that both ITGB2 and ICAM signaling were increased in gout flares, suggesting an important role for cell adhesion signaling." (PMID 38063198, 2023). "By comparing the information flow between gout flares and remission, we identified that 15 of 42 pathways were highly active during gout flares, including 9 pathways involved in inflammatory and immune responses, such as CCL, IL-16, MHC-II, CLEC, GLAECTIN, ITGB2, and ALCAM." (PMID 38063198, 2023).
Insulin resistance (2 papers, 2020 to 2024). Increased resistance towards insulin, that is, diminished effectiveness of insulin in reducing blood glucose levels. "Animal experiments have shown that lack of ItgaL can prevent insulin resistance, while lack of Itgb2 can provide protection." (PMID 32938406, 2020).
kidney inflammation (2 papers, 2018 to 2021). "Moreover, complement receptor genes CR1, ITGAM, ITGAX and ITGB2 showed a significant link between expression and kidney inflammation." (PMID 34326417, 2021).
malignant glioma (2 papers, 2022). A grade III or grade IV glioma arising from the central nervous system. "In cancer studies, ITGB2 was found to be significantly elevated in high-malignant gliomas and related to a worse prognosis." (PMID 36362654, 2022). "COX regression analysis shows that ITGB2 is an independent predictive marker of OS in malignant glioma patients." (PMID 36714574, 2022).
mastitis (2 papers, 2020 to 2023). Inflammation of breast tissue during lactation or postpartum due to an obstructed duct or infection. "In summary, TMT analyses elucidated the role of A2M, Itgb2, Thbs1, Fn1, ITIH4 and other proteins in the host innate response to S. aureus-induced mastitis." (PMID 32365127, 2020).
metastatic melanoma (2 papers, 2019 to 2025). A melanoma that has spread from its primary site to another anatomic site. "LAPTM5 (lysosomal-associated protein transmembrane 5) is one of the top genes significantly associated with longer survival in metastatic melanoma, and ITGB2 (integrin beta 2) co-expression with HLA-DR participates in signal transduction, cell adhesion, and motility in neoplastic melanocytes." (PMID 31212865, 2019). "In addition, BIN2, CMTM8, CXCL10, HCLS1, ITGB2, PTPN2, and RFTN2 were expressed at significantly higher levels in our B16 brain-derived variants compared with the parent B16-F0 and are also upregulated in human metastatic melanomas compared with primary cutaneous tumors." (PMID 39819494, 2025).
necrotizing enterocolitis (2 papers, 2022 to 2023). Necrotizing enterocolitis (NEC) is a devastating disease that affects mostly the intestine of premature infants. "Moreover, ITGB2 deficiency causes the hyperresponsiveness of the aberrant Toll-like receptor and leads to necrotizing enterocolitis pathogenesis." (PMID 36362654, 2022).
oral cancer (2 papers, 2020 to 2025). "In vivo, the effect of lactate from ITGB2 expressing CAFs was assessed by using a heterotopic oral cancer model." (PMID 33204328, 2020).
preeclampsia (2 papers, 2014 to 2023). Preeclampsia is a hypertensive disorder of pregnancy that is characterized by new-onset hypertension with proteinuria presenting after 20 weeks of gestation, and depending on mild or severe forms may initially present with severe headache, visual disturbances, and hyperreflexia. "In addition, these genes were elevated in the placentas of preeclampsia patients, including LRP1, COL6A1, ITGB2, and MMP3." (PMID 38003549, 2023).
serous ovarian cancer (2 papers, 2020 to 2023). "We first found that several genes, including ITGB2, were highly upregulated in serous ovarian cancer samples." (PMID 36980477, 2023). "Consistent with the previous findings, the expression of ITGB2 was increased significantly in serous ovarian cancer cells compared to normal ovarian epithelial cells both in protein and mRNA (messenger ribonucleic acid) levels." (PMID 36980477, 2023). "For this reason, we selected ITGB2 as the top candidate prognostic biomarker and focused on the role of ITGB2 in the serous ovarian cancer microenvironment." (PMID 36980477, 2023). "Since the upregulated ITGB2 was connected with the immune infiltration in serous ovarian cancer, we further applied Wikipathways and Reactome analyses for the potential molecular mechanism of ITGB2." (PMID 36980477, 2023). "Having demonstrated the potential relationship between ITGB2 and the immune infiltration in serous ovarian cancer patients via an integrated bioinformatics analysis, we deduced that this association may also be applicable to serous ovarian cancer patients." (PMID 36980477, 2023). "Subsequently, the gene and protein interactions with ITGB2 were identified via Metascape and STRING databases, and the high expression of ITGB2 could significantly affect the clinical outcome for patients with serous ovarian cancer." (PMID 36980477, 2023). "This indicates that the upregulation of ITGB2 might play a role in serous ovarian cancer." (PMID 36980477, 2023). "Among these, DH1, VEGFA, EPCAM, ITGB2, and CLDN7 had the highest correlation scores with serous ovarian cancer." (PMID 36980477, 2023). "Hence, for the sake of verifying the possible correlation between ITGB2 and serous ovarian cancer, we evaluated the expression and cellular localization of ITGB2 in serous ovarian cancer and non-ovarian tumor cells or tissues via a series of experiments." (PMID 36980477, 2023). "Additionally, ITGB2 was found to be positively expressed (27.27%) in the cytoplasm in serous ovarian cancer cells and tissues but was almost negative (5.93%) in the normal ovarian epithelial cells and non-tumor tissues, with a significant difference (p < 0.0001)." (PMID 36980477, 2023).
systemic sclerosis (2 papers, 2023). A chronic disorder, possibly autoimmune, marked by excessive production of collagen which results in hardening and thickening of body tissues. "ITGB2 was upregulated in PBMCs from systemic sclerosis (SSc) patients, which may participate in immune cell migration to involved tissues." (PMID 37614232, 2023).
tuberculosis (2 papers, 2018 to 2025). A chronic, recurrent infection caused by the bacterium Mycobacterium tuberculosis. "The “MAPK Signaling Pathway” includes genes like MAP3K2, PLA2G4A, and NFKB1, Lastly, the “Tuberculosis” pathway involves IFNGR2, ITGB2, and IL12B." (PMID 40621499, 2025). "The second network was tuberculosis (P = 1.03E−03), including ATP6V1H, cathelicidin 1 (CATHL1A), CTSS, ITGB2, myeloid differentiation primary response protein MyD88 (MYD88), and RAB5A." (PMID 30514405, 2018).
ankylosing spondylitis (1 paper, 2024). An autoimmune chronic inflammatory disorder characterized by inflammation in the vertebral joints of the spine and sacroiliac joints. "It has been shown that upregulation of ITGB2 synergistically affects leukocyte adhesion and migration to the vascular wall, thereby influencing the progression of ankylosing spondylitis." (PMID 38382092, 2024).
autism (1 paper, 2023). Persistent deficits in social interaction and communication and interaction as well as a markedly restricted repertoire of activity and interest as well as repetitive patterns of behavior. "For instance, in whole-genome DNA methylation analysis, the epigenetic dysregulation of C1q, C3, and ITGB2 (C3R) was reported in autism." (PMID 37107654, 2023). "Relatedly, whole-genome DNA methylation analysis uncovered epigenetic dysregulation of several complement genes such as C1Q, C3, and ITGB2 (C3R), as well as several other inflammatory genes (e.g., TNF-α, IRF8, and SPI1) in postmortem brain samples of patients with autism." (PMID 37107654, 2023).
bile acid synthesis disorder (1 paper, 2025). "Druggability evaluation highlighted four protein biomarkers, ITGB2, GP1BA, ACADSB and COX6B1, which are already targeted for dry eye disease, inflammation, seizure and bile acid synthesis disorder, respectively." (PMID 41340014, 2025).
brucellosis (1 paper, 2024). Brucellosis is a bacterial infection that spreads from animals to people via unpasteurized dairy products or by exposure to contaminated animal products or infected animals. "As the major contributor of potential inflammatory storm, many inflammatory response genes (e.g., ITGB2, OSM, FPR1, CEBPB, NINJ1) and canonical pro‐inflammatory cytokines (e.g., CXCL8, CCL3, CCL4, TNF, IL1B, S100A12) were expressed at higher levels in brucellosis patients than in healthy donors." (PMID 39135683, 2024).
co-infection (1 paper, 2025). "Notably, TGF-β signaling (TGFB1-TGFBR1-TGFBR2) was extinguished during HIV-mono infection yet reappeared in co-infection, whereas IL16-CD4 and CD40LG-(ITGAM/ITGB2) interactions disappeared with HIV-mono and did not recover, underscoring stage-specific rewiring of T-cell communication networks." (PMID 41394852, 2025).
dementia (1 paper, 2025). Loss of intellectual abilities interfering with an individual's social and occupational functions. "Despite most of these being more prominently dysregulated in AD (e.g., SDC4, ITGB2, MIF, and sTREM1), a small subset of proteins showed an opposite effect between these dementias (e.g., CHL1, GPC1, and CNTN5)." (PMID 40866991, 2025).
enthesopathy (1 paper, 2005). "Itgb2 was a candidate gene for enthesopathy and coincidentally for sialoadenitis, and was also highly expressed in group I." (PMID 15987484, 2005).
esophageal cancer (1 paper, 2025). A primary or metastatic malignant neoplasm involving the esophagus. "The importance of the ITGB2 pathway in MΦ function is emphasized by a positive correlation between ITGB2 expression and CD163+ MΦ infiltration in esophageal carcinoma where scRNA-seq analysis indicated a progressive increase in ITGB2 with the acquisition of a tumor-promoting phenotype." (PMID 40432828, 2025).
fibrosarcoma (1 paper, 2022). A malignant mesenchymal fibroblastic neoplasm affecting the soft tissue and bone. "Using the Spearman correlation index, we observed, as expected, that RHOB expression negatively correlated with the hypoxia-induced gene signature in lung, breast and fibrosarcoma tumors, while VIM and ITGB2 expression were generally positively correlated in all three cancer patient cohorts." (PMID 35681731, 2022).
fibrosis (1 paper, 2025). the formation of excess fibrous connective tissue in an organ or tissue in a reparative or reactive process. "Thus, aberrant ITGB2 expression suggested crosstalk between inflammatory responses and cardiac fibrosis in AF combined with SLE." (PMID 40102753, 2025).
keloid (1 paper, 2021). An irregularly shaped, elevated mark on the skin caused by deposits of excessive amounts of collagen during wound healing. "However, the pathological mechanism of ITGB2 and HSP90B1 in keloid formation is still unknown." (PMID 35082796, 2021).
leishmaniasis (1 paper, 2023). Infectious disease that is transmitted through the bite of hematophagous female phlebotomine sand flies. "For example, in “Leishmaniasis” and “Leukocyte Transendothelial Migration”, Itgb2 acted on NADPH oxidase through phagocytosis and calcium signaling pathways, leading to an impaired oxidative burst." (PMID 37063847, 2023).
major depressive disorder (1 paper, 2025). An episode of depression lasting two or more weeks without an intervening episode of mania. "Additionally, SPI1 has been identified as a shared gene between PD and major depressive disorder, while ITGB2 is upregulated in patients with unipolar depression." (PMID 40271183, 2025).
meningioma (1 paper, 2020). A generally slow growing tumor attached to the dura mater. "The global proteomic analysis of meningioma patients in the current study revealed perturbations in several components of Integrin including ITGAV, ITGB2, ITGA2B, and ILKAP." (PMID 32974197, 2020).
metastatic cancer (1 paper, 2024). A carcinoma which has spread from the original site of growth to another anatomic site. "The VCAM pathway, GDF pathway, MIF pathway, TNF pathway, CD137 pathway and ITGB2 pathway specifically appeared in metastatic cancer." (PMID 38365757, 2024).
metastatic prostate carcinoma (1 paper, 2020). A carcinoma that arises from the prostate gland and has spread to other anatomic sites. "ITGB2 levels are significantly increased in metastatic prostate cancer." (PMID 32664456, 2020).
myeloid leukemia (1 paper, 2017). A clonal proliferation of myeloid cells and their precursors in the bone marrow, peripheral blood, and spleen. "The severity of clinical manifestations of myeloid leukemia is directly related to the degree of CD18 (ITGB2) deficiency." (PMID 27878450, 2017).
Myocardial fibrosis (1 paper, 2025). "It has been demonstrated that activation of ITGB2 transcription can regulate macrophage tracking and contribute to myocardial fibrosis." (PMID 40102753, 2025).
myxofibrosarcoma (1 paper, 2023). A malignant fibroblastic neoplasm arising from the soft tissue. "ITGB2 participated in the YAP-induced cancer cell invasion by activating leukocyte-specific integrin β2 expression and the myxofibrosarcoma aggressiveness conferred by SKP2 amplification." (PMID 38022584, 2023).
osteoporosis (1 paper, 2015). A condition of reduced bone mass, with decreased cortical thickness and a decrease in the number and size of the trabeculae of cancellous bone (but normal chemical composition), resulting in increased fracture incidence. "Another study reported that ITGB2 deficiency predisposes mice to osteoporosis, thus highlighting the connection between ITGB2 and bone development." (PMID 25729860, 2015).
renal fibrosis (1 paper, 2023). A final common manifestation of a wide variety of chronic kidney diseases characterized by glomerulosclerosis and tubulointerstitial fibrosis. "In this study, ITGB2 was identified highly expressed in patients with IgAN, which might be associated with immune cell infiltration, renal fibrosis and decreased renal function." (PMID 36978098, 2023).
rosacea (1 paper, 2021). A chronic erythematous skin disorder that affects the face. "The results of RT-qPCR showed that carvedilol alleviated the elevated inflammatory cytokines (TNF-α, IL-6, and IL-8) and macrophage chemotactic factors (ITGAM, ITGB2) of rosacea-like skin, indicating that inflammation and macrophages are inhibited." (PMID 34322115, 2021). "Besides, macrophages in rosacea were supported by significant upregulation of cell markers of macrophages and upregulation of ITGB2 and ITGAM mRNA expression as well." (PMID 34322115, 2021).
skin infection (1 paper, 2023). An inflammatory process affecting the skin, caused by bacteria, viruses, parasites, or fungi. "Finally, mice lacking the integrin subunit Itgb2 (also called CD18), which is expressed on a variety of different white blood cells including neutrophils and macrophages, are susceptible to spontaneous skin infections by S. xylosus." (PMID 37533118, 2023).
squamous cell carcinoma (1 paper, 2025). A carcinoma arising from squamous epithelial cells. "Tier 2 proteins, supported by transcriptomic evidence but not sensitivity analyses, included AGRN, ITGB2, SEPTIN3 (adenocarcinoma) and DPP10 (squamous cell carcinoma)." (PMID 41340014, 2025).
tauopathy (1 paper, 2021). Neurodegenerative disorders involving deposition of abnormal tau protein isoforms (tau proteins) in neurons and glial cells in the brain. "This is consistent with the increase in Itgb2 (LFA-1) mRNA levels in the hippocampus of a mouse model of tauopathy." (PMID 33679799, 2021).
triple-negative breast carcinoma (1 paper, 2020). An invasive breast carcinoma which is negative for expression of estrogen receptor (ER), progesterone receptor (PR), and human epidermal growth factor receptor 2 (HER2). "It was found that high expression of Itgb2 in triple-negative breast carcinoma exerted effects on the prognosis of patients." (PMID 33679872, 2020).
ulcerative colitis (1 paper, 2021). An inflammatory bowel disease involving the mucosal surface of the large intestine and rectum. "In line with our study, single cell RNA-sequencing of colonic T cells showed presence of multiple CD8+ Trm cell clusters, of which a KLRG1+EOMES+ITGB2+ subset is enriched in ulcerative colitis, and the CD103+ population in healthy control subjects." (PMID 34224909, 2021).
uveal melanoma (1 paper, 2024). A melanoma derived from melanocytes of the uveal tract. "Apart from its immune functions, ITGB2 promotes the metastasis of uveal melanoma by regulating ECM signature." (PMID 38814534, 2024).
vasculitis (1 paper, 2023). "ITGB2 (CD18) a receptor for ICAM1, ICAM2, ICAM3, and ICAM4, is a potential mechanistic biomarker for vasculitis." (PMID 38274452, 2023).